HIF1A (hypoxia inducible factor 1 subunit alpha)
Diseases named in the same sentence as HIF1A in open-access papers (continued):
Sharing a sentence is not in itself a finding about the gene and the disease.
cancer (continued). "Several studies have demonstrated that SPHK-1 controls the level of HIF-1α during hypoxia in cancer cells." (PMID 27581969, 2016). "In our previous study, HIF-1a was found overexpressed in many human cancers and various cell types, and the levels of HIF-1a activity were correlated with tumorigenicity, angiogenesis, and metastasis." (PMID 27456341, 2016). "This suggests that PKM2 participates in the intricate cross-talk between NF-κB and HIF-1α and urged us to elucidate the potential chronology of the signaling events in hypoxic cancer cells leading to VEGF secretion." (PMID 26739387, 2016). "We found that JNK2 inhibition restored expression of HIF-1α target genes and suppressed expression of pro-apoptotic genes in docetaxel-treated cancer cells under hypoxic conditions." (PMID 27263528, 2016). "These new findings are in line with earlier Western analyses using human cancer cell lines that report stabilization of endogenous HIF‐1α protein upon treatment with these same compounds." (PMID 26729005, 2016). "The purpose of the present study was to elucidate the mechanism by which docetaxel regulates HIF-1α expression and induces cancer cell death under hypoxic conditions." (PMID 27263528, 2016). "In cancers, the active form of HiF-1α is responsible for shifting cellular metabolism from aerobic to anaerobic (i.e., the “Warburg Effect”) and for increasing vascularization through the upregulation of angiogenic proteins." (PMID 26689994, 2016). "In this study, pristimerin significantly decreased cell viability under hypoxia more than it did under normoxia, which connotes the potential of pristimerin treatment-resistant cancer cells, given that HIF-1α promotes cancer resistance." (PMID 27581969, 2016). "Numerous studies have documented that melatonin exhibits antiangiogenic actions, in part, by downregulating VEGF and HIF-1α in several cancers via different mechanisms; the cancer types included breast, prostate, colon, liver, and pancreatic cancer." (PMID 27102150, 2016). "This action on PTEN reinforces the role of RSUME on several specific targets related to cancer and inflammation, such as HIF-1α, I-κB, GR and pVHL." (PMID 27506944, 2016). "We also used IHC staining to confirm that the expression of HIF-1α decreased in BAY 87-2243 treated cancer tissues compared to control group." (PMID 27016414, 2016). "Most importantly, we revealed a novel mechanism whereby Daxx is downregulated by HIF-1α, thus enabling initiation of metastasis in cancer cells." (PMID 28004751, 2016). "Activated PHD1, in turn, decreases HIF-1α stability in hypoxic cancer cells by promoting its ubiquitin-proteasome-mediated degradation, thereby inducing cancer cell death." (PMID 27263528, 2016). "In this report we demonstrate that Rab25 regulates HIF-1α protein expression in an oxygen independent manner in a panel of cancer cell lines." (PMID 26967059, 2016). "To confirm this interpretation, we evaluated compound mice carrying a tissue-specific gene knock out of HIF1α in the oncogene-expressing cancer cells." (PMID 27134166, 2016). "LDHA is known to be regulated by other oncogenes such as HIF-1a during cancer progression, thus cancer cells have expanded regulatory mechanism to confer metabolic advantages in the advanced stages of diseases." (PMID 27150057, 2016). "An association with increased mortality has also been observed in cancers with poorly oxygenated areas and in cancers expressing HIF-1α at high levels." (PMID 27066002, 2016). "Collectively, this study reveals a role for NQO1 in the oxygen-sensing pathway that regulates HIF-1α stability in cancers." (PMID 27966538, 2016). "Overexpression of HIF-1α was found in various types of cancers of both human and mice and is an unfavorable prognostic factor in different cancers." (PMID 26872370, 2016). "VEGF and HIF-1-α are, furthermore, overexpressed in several types of human cancers, especially with HIF-1-α in metastatic OS." (PMID 26775693, 2016).
cancer (continued). "The vascular endothelial growth factor (VEGF) has been reported to be modulated by miR-20b via the hypoxia-inducible factor 1-alpha (HIF1α) in response to hypoxia, whereas FoxO1 was regulated by miR-27a in cancer cells, and SIRT-1 by miR-9 in stem cells." (PMID 27144581, 2016). "To date, ZFP91 has been shown to be a key factor in activation of noncanonical NF-κB signaling pathway as well as to be involved in HIF-1α signaling in cancer cells." (PMID 27975057, 2016). "HIF-1α is correlated with poor cancer prognosis and chemotherapeutic resistance in various cancers, and many HIF-1α inhibitors have been studied as potential anticancer agents." (PMID 27611801, 2016). "These pathways in cancer progression included cytokine/NF-kB, HIF-1α, and WNT signaling, all of which are known to play a role in regulating BCSCs and have been associated with EMT." (PMID 27285982, 2016). "At the transcriptional level, increased proliferation and migration of endothelial cells exposed to cancer cells modified by senescent HPMCs was regulated by HIF-1α, NF-κB/p50 and AP-1/c-Jun." (PMID 26433963, 2016). "Hypoxic cancer cells can also be eliminated or sensitized to treatment by inhibition of HIF-1α-dependent transcription through agents such as the cardiac glycoside digoxin, acriflavine, and the small molecule HIF-1α inhibitor PX-478." (PMID 27608848, 2016). "Taken together, a novel MDH2 inhibitor, compound 7, suppressed HIF-1α accumulation via reduction of oxygen consumption and ATP production, integrating metabolism into anti-cancer efficacy in cancer cells." (PMID 27611801, 2016). "In support of this HIF-1α-stabilizing role of septin 9, disruption of normal assembly-disassembly of septin oligomers with FCF induces degradation of HIF-1α, and inhibition in HIF-1α transcriptional activity in various cancer cell types." (PMID 28066764, 2016). "In this study, we initially validated that hypoxia and HIF-1α decreased sensitivity of cancer cells to cisplatin in OSCC cell lines." (PMID 27762347, 2016). "Docetaxel pretreatment enhanced the polyubiquitination and proteasome-mediated degradation of HIF-1α, and increased cancer cell death under hypoxic conditions." (PMID 27263528, 2016). "VH298 induced concentration-dependent accumulation of HIF-1α levels after 2 h treatments in immortalized HeLa cancer cells, with detectable HIF-1α bands visible as low as 10 μM concentration." (PMID 27811928, 2016). "HIF-1α has been shown to upregulate the expression of PD-1 ligand on cancer cells, thus inhibiting T cell-mediated cytotoxicity." (PMID 26870036, 2016). "Lipogenic genes are upregulated in response to HIF-1α expression, suggesting that de novo lipogenesis can be enhanced in cancer cells under hypoxia (route 13)." (PMID 27589734, 2016). "To further explore molecular alterations in premalignant and malignant tumors with high stromal HIF-1α, we performed a Gene Set Enrichment Analysis (GSEA)." (PMID 27634881, 2016). "Taken together, these findings suggest that pristimerin can exert an anti-cancer activity by inhibiting HIF-1α through the SPHK-1 pathway." (PMID 27581969, 2016). "Although it is unclear how lactic acid acts differentially trigger macrophage polarization via HIF1α stabilization, it has been reported in cancer cells that lactic acid stabilizes HIF1α in cells relying on OXOPHOS but not in cells engaging aerobic glycolysis." (PMID 26885366, 2016). "The prognostic significance of HIF-1α in tumors has been widely studied and literatures have identified that HIF-1α expression is an indicator for poor survival in several cancers." (PMID 27606158, 2016).
cancer (continued). "Collectively, these findings reveal a novel mechanism that mediates the regulation of HIF-1α and anticancer effects of docetaxel in hypoxic cancer cells." (PMID 27263528, 2016). "A recent study demonstrated that HIF-1α expression directly regulates de novo EMT-related gene expression, causing an alteration in phenotype through EMT in a cancer metastasis model." (PMID 27095949, 2016). "On the contrary, in non-cancer epithelial cells rapamycin only marginally inhibited desferrioxamine-induced HIF-1α and transcription." (PMID 27821815, 2016). "Induction of HIF-1α was observed upon expression of Rab25 across a panel of cancer cell lines of different origins." (PMID 26967059, 2016). "Cancer cells were sensitive to UA treating after the silencing of HIF-1α and the response of Hypoxic pathway reporter to UA was suppressed when HIF-1α was over expressed." (PMID 27708244, 2016). "Hypoxia and alterations of hypoxic signaling, such as that demonstrated by hypotaurine on HIF-1α, have been well described as mechanisms of cancer development and growth." (PMID 26934654, 2016). "HIF-1α mediates a metabolic switch from oxidative phosphorylation to lactate fermentation and controls glycolytic gene expression, further supporting cancer cell survival." (PMID 27023612, 2016). "Phosphorylated STAT3 under hypoxic conditions has been shown in multiple cancer cell lines to stabilize and simultaneously bind with HIF-1α to separate sites on the VEGF promoter, in order to maximally induce expression." (PMID 27529341, 2016). "To achieve this, we took advantage of a previously established shRNA-based stable inhibition of HIF-1α in a number of cancer cell lines." (PMID 26760764, 2016). "At the same time, glycolytic adenosine triphosphate (ATP) production and the transporter induced over-expression of HIF-1α contribute to a decrease in the cytoplasmic retention of anti-cancer agents." (PMID 27825361, 2016). "It has been shown that interaction between NICD and HIF-1α increases the expression of Snail and Slug, which enhance cancer invasion and migration." (PMID 26989421, 2016). "Here we investigated the effects of bile acids on the cancer growth and migratory potential of cell lines where HIF-1α is known to be active under hypoxic conditions." (PMID 27416726, 2016). "Further, more understanding of the kinase inhibitor specificities toward HIF-1α, metabolic and toxic side effects would be needed to optimize cancer therapy." (PMID 26942179, 2016). "HIF-1α represents a central protein involved in different pathways that are important for the survival of cancer cells in early cancer disease progression." (PMID 27044404, 2016). "Under hypoxic conditions, stabilized hypoxia-inducible factor (HIF)-1α downregulates Daxx expression and promotes cancer invasion, whereas re-expression of Daxx represses hypoxia-induced cancer invasion." (PMID 28004751, 2016). "Expression of HIF-1α and LDH-5 are found to be correlated and associated with poor prognosis of many cancers." (PMID 26791262, 2016). "ENO1 is demonstrated to be up-regulated in the hypoxic cancer and brain cells under the control of the Hypoxia-inducible factor 1-α (HIF-1α)." (PMID 26882120, 2016). "As a transcription factor, hypoxia-inducible factor 1α (HIF-1α) is a master regulator responsible for the induction of genes that assist cancer cells to survive and metastasize from normoxia to hypoxia." (PMID 26988756, 2016). "Collectively these results indicate that the levels of PHF8, HIF1α and HIF2α were all elevated in the post-castration cancer tissues." (PMID 27991916, 2016). "Hypoxia is recognized as a selection pressure to promote cancer metastasis, and overexpression of HIF-1α in cancer cells is known to promote cancer metastasis in several reports." (PMID 27167192, 2016). "This study provides the first demonstration that WNT11 expression is regulated by hypoxia and the HIF-1α pathway in normal and cancer-derived cells." (PMID 26861754, 2016).
cancer (continued). "Digoxin, a cardiac glycoside, it has been shown to have anti-cancer activity due to the inhibition of HIF1A synthesis, in vitro and in vivo in several solid tumors." (PMID 26859576, 2016). "Most of the literature available on other cancer entities suggests that overexpression of HIF-1α is an indicator of poor prognosis, while some suggest contradictory results." (PMID 27780920, 2016). "For instance, it has been observed that HIF-1α induced the expression of miR-210, which subsequently affected mitochondrial metabolism, cell cycle progression, DNA repair, and cancer formation." (PMID 27114850, 2016). "Hypoxia-inducible factor-1α (HIF-1α) is well known for being the transcriptional factor that allows cellular adaptation to hypoxia surrounding cancer tissues." (PMID 26909598, 2016). "HIF1α in turn activates ROS generation, establishing a feed-forward loop where HIF1α supports its stability to promote cancer cell survival and malignant progression." (PMID 27455839, 2016). "Recently, PKM2 was reported to regulate glucose metabolism by functioning as a coactivator for HIF-1α in cancer cells." (PMID 26739387, 2016). "Inducible glutamine metabolism via HIF-1α is also crucial for cancer cells exposed to hypoxia (route 6)." (PMID 27589734, 2016). "Hypoxia-inducible factor 1a (HIF1a) is an essential transcription factor for cellular adaptation to hypoxia in cancer." (PMID 28033431, 2016). "PI3K induces the accumulation, activation, and stabilization of HIF-1α proteins during hypoxia in cancer cells." (PMID 27581969, 2016). "We found that PHD1 inhibition partially restored HIF-1α accumulation and activation in docetaxel-treated cancer cells under hypoxic conditions and reduced docetaxel-induced cell death." (PMID 27263528, 2016). "Further investigations are warranted to formally demonstrate that HIF-1α is needed to trigger the metabolic reprogramming in HNSCC cancer cells." (PMID 27791989, 2016). "Collectively, these findings indicate that docetaxel decreases HIF-1α protein stability in hypoxic cancer cells." (PMID 27263528, 2016). "Loss of CSL unleashed a hypoxic response during normoxic conditions, manifested by stabilization of the HIF1α protein and acquisition of a polyploid giant-cell, cancer stem cell-like, phenotype." (PMID 27066863, 2016). "CD24 overexpression in HIF-1α-knockdown cancer cells rescued this decrease while HIF-1α overexpression in CD24-knockdown cells did not." (PMID 27706047, 2016). "Metabolic switch to aerobic glycolysis in cancer cells involves the mTOR-mediated expression of glycolytic enzymes through the activation of HIF-1α, NFκB, and c-Myc." (PMID 26918353, 2016). "To delineate how docetaxel-induced HIF-1α degradation occurs in hypoxic cancer cells, we evaluated the expression of HIF-1α regulators." (PMID 27263528, 2016). "Docetaxel also activated the prolyl hydroxylase, PHD1, in hypoxia, and pharmacological inhibition or siRNA-mediated knockdown of PHD1 prevented docetaxel-induced HIF-1α degradation and cancer cell death." (PMID 27263528, 2016). "A major mechanism through which hypoxia affects cancer cell behavior is induction of the transcription factor HIF-1α (hypoxia induced factor-1α)." (PMID 27608848, 2016). "PHD1 inactivation increased HIF-1α transactivation and effectively reduced docetaxel-induced cancer cell death under hypoxic conditions." (PMID 27263528, 2016). "Up to date, a key signaling molecule regulating the angiogenesis in human cancers has been identified, that is the hypoxia-inducible factor-1 alpha (HIF-1α), which transcriptional up-regulates several proangiogenic chemokines, including VEGF." (PMID 27806334, 2016). "XBP1 cooperation with HIF-1α has been shown to protract a transcriptional program supporting neo-angiogenesis and cancer stem cell (CSC) maintenance." (PMID 27540529, 2016).
cancer (continued). "Overexpression of HIF-1α was found in various human cancers, HIF-1α downstream genes have been identified that are widely involved in the malignant features of tumors, including angiogenesis, invasion, metastasis, and drug resistance." (PMID 27029070, 2016). "Thyroid hormones have also been shown to promote angiogenesis in cancer cells by upregulating HIF-1α." (PMID 27123358, 2016). "It has been confirmed by a number of studies that expression of HIF-1α is correlated with poor prognosis in various cancers, including gastric, esophageal and lung cancers." (PMID 27606158, 2016). "Here, we assessed HIF-1α destabilisation in three cancer cell lines using two independent methods; immunofluorescence with an anti-HIF-1α antibody in A-549, MCF-7 and DU-145 cells and an anti-HIF-1α subunit ELISA in DU-145 cells." (PMID 27416726, 2016). "Deregulation of AHR and HIF-1α activity can promote various disease states including cancer proliferation, and ARNT has been shown to be essential in supporting these pathophysiological characteristics." (PMID 26909609, 2016). "HIF-1α overexpression in human cancers is considered as consequences of intra-tumoral hypoxia as well as genetic alterations." (PMID 26872370, 2016). "In cancer cells, HIF‐1α induces the expression of several glycolytic protein isoforms that differ from those found in non‐malignant cells, including glucose transporters and a plethora of enzymes." (PMID 27138568, 2016). "One study has even reported that EVs can deliver a biologically active transcriptional factor, Hif-1α, to a recipient cancer cell line." (PMID 28936249, 2016). "It seems that ROS affect the HIF-1α signaling in a context-dependent manner and differently in cancer and ischemia." (PMID 27114850, 2016). "Together, these observations provide a novel mechanistic link between disulfide bond-mediated PHD2 dimerization and consequently HIF-1α stabilization upon oxidative stress in several cancer cells." (PMID 26740011, 2016). "Hypoxia and HIF-1α can increase expression of drug efflux pumps, induce cell cycle arrest in G1 or G2, and alter metabolism to facilitate cancer cell survival." (PMID 27608848, 2016). "In this study, we show that Daxx is a negative regulator of hypoxia-induced EMT and cancer metastasis that acts by inhibiting the HIF-1α/HDAC1/Slug pathway." (PMID 28004751, 2016). "On the contrary, pathways such as FGF Signaling, Clathrin-mediated Endocytosis Signaling, HIF1A Signaling, and etc. were only uniquely observed as deregulated in a specific cancer type." (PMID 27876019, 2016). "Anchorage-independent cell growth is a representative property of cancer cells with tumorigenic potential, and it has been reported to occur depending on HIF-1α." (PMID 27613833, 2016). "PKM2 physically interacts with HIF-1α in the nuclei of hypoxic human cancer cells and promotes transactivation of HIF-1α target genes by enhancing the recruitment of p300 to HRE sites." (PMID 26739387, 2016). "The regulation of HIG2 expression at the transcriptional level is solely dependent on HIF-1α in cancer cells." (PMID 27589734, 2016). "HIF-1α activation contributes to the metabolic reprogramming of cancer cells by impairing mitochondrial phosphorylation and the subsequent stimulation of aerobic glycolysis." (PMID 27455839, 2016). "Next, the inhibitory effects of sMEK1 on HIF-1α expression under hypoxic conditions in SKOV-3 cancer cells were assessed." (PMID 26378810, 2015). "Different expression patterns and roles of HIF-1α/2α in various tumors indicate the importance of their specificity for cancer survival and propagation." (PMID 26210994, 2015).